VPS39 (VPS39 subunit of HOPS complex)
Description:
Regulator of TGF-beta/activin signaling, inhibiting SMAD3- and activating SMAD2-dependent transcription. Acts by interfering with SMAD3/SMAD4 complex formation, this would lead to inhibition of SMAD3-dependent transcription and relieve SMAD3 inhibition of SMAD2-dependent promoters, thus increasing SMAD2-dependent transcription. Does not affect TGF-beta-induced SMAD2 or SMAD3 phosphorylation, nor SMAD2/SMAD4 complex formation. Plays a role in vesicle-mediated protein trafficking to lysosomal compartments including the endocytic membrane transport and autophagic pathways. Acts as a component of the HOPS endosomal tethering complex. This complex is proposed to be involved in the Rab5- to-Rab7 endosome conversion probably implicating MON1A/B, and via binding SNAREs and SNARE complexes to mediate tethering and docking events during SNARE-mediated membrane fusion. The HOPS complex is proposed to be recruited to Rab7 on the late endosomal membrane and to regulate late endocytic, phagocytic and autophagic traffic towards lysosomes. Involved in homotypic vesicle fusions between late endosomes and in heterotypic fusions between late endosomes and lysosomes. Required for fusion of endosomes and autophagosomes with lysosomes.
Synonyms: hVam6p; KIAA0770; TLP; VAM6
Tractability: Antibody: UniProt places it where antibodies can reach, with high confidence. PROTAC: ubiquitination databases record sites on it; its protein half-life has been measured.
Gene: Protein-coding gene on chromosome 15 (42,158,701 to 42,208,326, reverse strand). Ensembl gene ENSG00000166887.
Subcellular location: Cytoplasm; Lysosome membrane; Late endosome membrane
Pathways (Reactome):
Disease: SARS-CoV-2 modulates autophagy
Gene Ontology:
Molecular function: molecular adaptor activity; protein binding; small GTPase binding
Biological process: autophagosome-lysosome fusion; autophagy; endocytic recycling; endosomal vesicle fusion; endosome to lysosome transport; late endosome to lysosome transport; autophagosome maturation; regulation of SNARE complex assembly; vacuole fusion; vesicle-mediated transport; intercellular transport; intracellular protein transport
Cellular component: HOPS complex; late endosome; late endosome membrane; lysosomal HOPS complex; lysosomal membrane; endosome membrane; AP-3 adaptor complex; cytoplasm; endomembrane system
Genetic constraint (gnomAD): Loss-of-function variants: 69 observed, 122.06 expected, observed/expected ratio (o/e) 0.57, 90% interval 0.47 to 0.69. The upper end of that interval is the gene's LOEUF score, 0.69, which puts it in group 2 of 6, group 1 being the genes least tolerant of losing a copy. Missense variants: 817 observed, 1,089.9 expected, observed/expected ratio (o/e) 0.75, 90% interval 0.71 to 0.79. Synonymous variants: 378 observed, 415.55 expected, observed/expected ratio (o/e) 0.91, 90% interval 0.83 to 0.99.
Homologues: Orthologues: chimpanzee VPS39 (99% identical), macaque VPS39 (99% identical), pig VPS39 (99% identical), rabbit VPS39 (99% identical), dog VPS39 (98% identical), mouse Vps39 (97% identical), guinea pig VPS39 (97% identical), rat Vps39 (94% identical), zebrafish vps39 (83% identical), tropical clawed frog vps39 (80% identical), Drosophila melanogaster Vps39 (37% identical), Caenorhabditis elegans vps-39 (32% identical). Paralogues in human: TGFBRAP1 (24% identical).
Diseases named in the same sentence as VPS39 in open-access papers:
VPS39 is named in the same sentence as 15 diseases in open-access papers, as found by Europe PMC text mining. Sharing a sentence is not in itself a finding about the gene and the disease. The quoted sentences say what the papers report.
COVID-19 (2 papers, 2024 to 2025). A disease caused by infection with severe acute respiratory syndrome coronavirus 2. "By uncovering the functional interaction between ORF3a and VPS39, we have identified a viral-host interaction that could serve as a potential target to address the lipid dysregulation associated with COVID-19." (PMID 39605369, 2024).
breast carcinoma (1 paper, 2019). "The VPS39 is a critical subunit of the homotypic fusion and vacuole protein sorting (HOPS) late endosomal complex and plays an important role in the cellular invasion in breast cancer." (PMID 31675998, 2019).
ciliopathies (1 paper, 2020). "In conclusion, we now report the characterization of an additional player in the field of autophagy-mediated control of ciliogenesis, the VPS39 protein, which could represent a new biological target for the recovery of the cilia-associated phenotypes observed in kidneys of ciliopathy patients." (PMID 32077937, 2020).
Glucose intolerance (1 paper, 2021). Glucose intolerance (GI) can be defined as dysglycemia that comprises both prediabetes and diabetes. "Glucose uptake was significantly reduced in extensor digitorum longus (EDL) muscle of Vps39+/− versus WT mice, demonstrating that VPS39-deficiency is associated with glucose intolerance and impaired muscle function in mice, which is in line with what is seen in patients with T2D." (PMID 33893273, 2021). "In conclusion, our data collected from human and mouse converge into a model where VPS39-deficiency leads to impaired autophagy and metabolism, epigenetic alterations, insufficient upregulation of myogenic regulators, and thereby poor myogenesis and glucose intolerance." (PMID 33893273, 2021). "Vps39+/− mice exhibit glucose intolerance and expression changes of genes affecting epigenetics, autophagy, and metabolism in muscle." (PMID 33893273, 2021). "Indeed, Vps39+/− mice showed glucose intolerance and decreased glucose uptake in muscle." (PMID 33893273, 2021).
Hyperglycemia (1 paper, 2021). An increased concentration of glucose in the blood. "Based on this we propose that the lower VPS39 expression in individuals with T2D could be one mechanism that contributes to a dysfunctional skeletal muscle phenotype and hyperglycemia." (PMID 33893273, 2021).
Insulin resistance (1 paper, 2021). Increased resistance towards insulin, that is, diminished effectiveness of insulin in reducing blood glucose levels. "On the basis of the present data, we propose a model for T2D in which low VPS39 levels contribute to impaired muscle regeneration and insulin resistance through metabolic and epigenetic changes." (PMID 33893273, 2021). "We found differential expression of several genes between the T2D and control groups, and although we focused this study on dissecting the role of VPS39 in muscle cells, other genes do also contribute to the muscle dysfunction and insulin resistance seen in T2D." (PMID 33893273, 2021).
renal cystic disease (1 paper, 2020). "Our study now provides a novel player of the cilia-autophagy axis in kidneys, VPS39, whose expression levels are significantly increased in two different murine models of renal cystic disease." (PMID 32077937, 2020). "In addition, we showed that VPS39 protein levels increase in mutant kidneys of two different murine models of inherited renal cystic disease (i.e. OFDI and ADPKD)." (PMID 32077937, 2020).
type 2 diabetes (1 paper, 2021). "Here, the authors report alterations in muscle stem cells from individuals with type 2 diabetes that may contribute to these phenotypes through VPS39 mediated effects on autophagy and epigenetics." (PMID 33893273, 2021).
infection (8 papers, 2014 to 2025). The state of being infected such as from the introduction of a foreign agent such as serum, vaccine, antigenic substance or organism. "Although ZIKV initially activates autophagy in TM, it impairs the overall autophagic flux during infection by modulating the VPS39, a HOPS complex, and STX17, a SNARE complex protein, to inhibit autophagosomal maturation." (PMID 40920489, 2025). "ASFV CP204L interacts with VPS39, blocking its association with the lysosomal HOPS complex, and loss of VPS39 reduces the levels of virus proteins synthesized in the early phase of infection and delays ASFV replication." (PMID 38169281, 2024). "In support of these findings, we found that ORF3a or Vps39 depletion greatly reduced the viral load during infection." (PMID 38448435, 2024). "CP204L predominantly interacts with VPS39 early in infection, whereas A137R is expressed later during infection." (PMID 39339953, 2024). "As expected based on ASFV growth kinetics, the most profound changes were observed at 8 h after infection, whereas at later stages of infection, the levels of viral proteins in VPS39-KO cells stabilized and were comparable with those observed in CTRL-KO cells." (PMID 36722971, 2023). "In the cells expressing CP204L after transfection or after infection, VPS39 aggregates were largely separated from LAMP1-marked lysosomes, which concentrated in the area near the nucleus." (PMID 36722971, 2023). "Progeny virus titers were reduced by 1.5-log10 in VPS39-KO compared to control cell supernatant 24 h after infection." (PMID 36722971, 2023). "Although virus replication and protein synthesis were reduced in VPS39-deficient cells, especially early during infection, this effect did not correlate with the 4-order-of-magnitude reduction observed with CP204L inhibition." (PMID 36722971, 2023). "SARS-CoV-2 virus could block autophagy by infection or expression of ORF3a to sequestrate the HOPS component VPS39 and impaired the assembly of the STX17-SNAP29-VAMP8 SNARE complex." (PMID 35923698, 2022). "Furthermore, we show that loss of VPS39 reduces the levels of virus proteins synthesized in the early phase of infection and delays ASFV replication but does not completely inhibit it." (PMID 36722971, 2023). "Whereas VPS39 remains concentrated in the VF throughout the infection, some CP204L in the late stage of infection (after 24 h) showed cytoplasmic distribution." (PMID 36722971, 2023). "During infection, both viral proteins A137R and CP204L engage with a CHCR domain spanning amino acids 271–541, indicating their competitive interactions for binding to VPS39 with cellular partners and among themselves." (PMID 39339953, 2024). "Moreover, our observations suggest that VPS39 is an important host factor that regulates the early steps of infection but is not essential for ASFV replication." (PMID 36722971, 2023).
tumor (3 papers, 2011 to 2022). "In line with this, a recent study has shown that Vps39, along with Rab2a, controls exocytosis of late endosomal MT1-MMP, an essential metalloprotease required for extracellular matrix remodeling and tumor invasion." (PMID 28325809, 2017). "An MCV LT domain that is conserved in both tumor-derived and wild-type MCV strains interacts with the cytoplasmic vacuolar sorting protein, hVam6p (also known as Vps39), a component of the HOPS (homotypic fusion and protein sorting) complex involved in late endosomal and lysosomal fusion." (PMID 21799863, 2011).
cancer (2 papers, 2019 to 2022). A tumor composed of atypical neoplastic, often pleomorphic cells that invade other tissues. "Collectively, the splicing modulation of VPS39, ZNF207, and TBC1D4 in curcumin-treated HNC cells provides the basis for future investigation of the role of cancer-specific isoforms of these genes in tumorigenesis." (PMID 31675998, 2019).
VPS39 also shares sentences with these, for which no sentence is quoted: viral infection (2 papers); AIDS (1); ovarian carcinoma (1); Salmonella Infections (1).